MMP9 (matrix metallopeptidase 9)
Diseases named in the same sentence as MMP9 in open-access papers (continued):
Sharing a sentence is not in itself a finding about the gene and the disease.
colitis (continued). "Regarding the inflammatory parameters analyzed in our studies, 15d-PGJ2 administration inhibits MMP-9, iNOS and COX-2 expression, MPO activity and MDA accumulation in inflammation-related pathologies such as restraint stress exposure, cerebral ischaemia, and colonic inflammation and dysfunction." (PMID 20929574, 2010). "Interestingly, the silencing of Mmp3 by siRNA markedly ameliorated DSS-induced colitis in mice, whereas knockout of Mmp9 or its pharmacological inhibition surprisingly had no obvious effect on the progression of DSS- and TNBS-stimulated colitis in the murine model." (PMID 36901742, 2023). "Thus, MMP-9 rather than MMP-2 might play an important role in the pathogenesis of DSS-induced colitis via degradation of extracellular matrix proteins in ulcerative colitis." (PMID 36289761, 2022). "The combination of the MMP9 inhibitor IN-1 with Homo demonstrated no synergistic effect, it confirmed the role of the MMP9-RLN2 axis in colitis modulation." (PMID 40529132, 2025). "In general, in line with our data obtained in MMP-9−/− mice, pharmacological inhibition of MMP-9 did not improve colitis phenotypes." (PMID 28561062, 2017). "Here we show that IBD clinical and histopathological parameters found in wild type mice challenged with three different models of colitis, acute and chronic dextran sodium sulphate (DSS), and acute 2,4,6-trinitrobenzenesulfonic acid-induced colitis are not attenuated in MMP-9 knockout mice." (PMID 28561062, 2017).
coronary artery disease (116 papers, 2007 to 2026). "In 1127 patients with confirmed coronary artery disease, higher baseline plasma MMP9 concentrations were associated with increased cardiovascular mortality over a mean follow-up of 4.1 years (62.2 ng/mL in fatal events vs. 47.8 ng/mL in survivors; p < 0.0001)." (PMID 40566560, 2025). "High circulating levels of MMP-9 have also been linked to increased mortality in patients with coronary artery disease." (PMID 39466144, 2025). "It was also found that in patients with coronary artery disease, higher MMP-9 levels are an independent risk factor for cardiovascular mortality." (PMID 38540214, 2024). "Polymorphisms in genes associated with the regulation of calcium levels (CASR, CYP24A1, CARS, DGKD, DGKH/KIAA0564 and GATA3) and metalloproteinases (MMP-3 and MMP-9) were also associated with an increased risk of coronary artery disease and AMI." (PMID 38478535, 2024). "On the contrary, a loss in serum MMP-9 after psychosocial stress was reported in HC and in patients with coronary artery disease." (PMID 36768263, 2023). "Gene analysis in a sample of 584 male patients showed a relationship between the 1562C > T polymorphism in the MMP9 gene and coronary heart disease severity." (PMID 35842645, 2022). "The MMP‐9 plasma levels are elevated in coronary heart disease and associated with atherosclerotic plaque destabilization, acute coronary events and mortality in these patients." (PMID 31932967, 2021). "MMP9 is an independent risk factor for coronary artery disease in KD, and the MMP-9 mRNA level was increased in KD patients with coronary artery disease and decreased at least 3 weeks after IVIG treatment." (PMID 33868359, 2021). "The rs3918242 minor allele is associated with an exaggerated plasma MMP-9 response in coronary artery disease patients and, in turn, elevated plasma MMP-9 independently predicts cardiovascular mortality as well as severity of MI." (PMID 33579197, 2021). "Disease progression in coronary artery disease was previously associated with an increasing MMP-9/TIMP‐1 ratio in circulating CD14+ monocytes." (PMID 31932967, 2021). "MMP-9 is a strong independent predictor of atherosclerotic plaque instability in stable coronary heart disease (CHD) patients, where MMP-9 levels are positively associated with the size of the necrotic core of coronary atherosclerotic plaques." (PMID 32486345, 2020). "Polymorphism (rs3918242) in the MMP9 gene has been reported to be associated with coronary artery disease (CAD)." (PMID 29507703, 2018). "Studies have consistently supported the correlation of MMP-9 rs3918242 polymorphism correlated with increased susceptibility to a variety of diseases, including coronary artery diseases." (PMID 28390432, 2017). "The results suggested that C(-1562)T MMP-9 transition is associated with premature ischemic heart disease in Polish patients." (PMID 26330106, 2015). "A previous study on a Polish population revealed that the −1562C/T polymorphism in the MMP-9 gene is significantly correlated with ischemic heart disease." (PMID 25667675, 2015). "The incidence of coronary heart disease has been reported to be associated with the serum level of MMP-9." (PMID 26692905, 2015). "MMP-9 high levels and activity have been considered independent predictors for the development of coronary artery diseases and are associated with increased cardiovascular risk in subjects with MetS." (PMID 26557715, 2015). "The MMP-9 −1562 C/T polymorphism has furthermore been shown as a risk factor for coronary artery disease (CAD)." (PMID 25191702, 2014). "Accordingly, a number of studies have associated elevated serum levels of MMP-9 with many chronic inflammatory conditions including coronary artery disease (CAD), COPD, arthritis and metabolic syndrome." (PMID 23825535, 2013). "MMP-9 (-1562C>T) polymorphism associated with higher plasma MMP-9 activity and contributed to the development of early onset coronary artery disease." (PMID 28348691, 2012).
coronary artery disease (continued). "Despite several evidences of the role of MMP-9 polymorphism in coronary artery disease, some publications indicated conflicting conclusions regarding role of MMP-9 polymorphism in severity of coronary artery disease." (PMID 28348691, 2012). "Recently, another study showed that PPARγ gene C161→T substitution was associated with reduced risk of coronary artery disease through modulation of pro-inflammatory cytokines, MMP-9 and TNF-α expression in a Chinese population." (PMID 20334678, 2010). "The association of MMP9 status with a progression of coronary heart disease has also been confirmed by molecular genetic studies that used the functional −1562 C/T polymorphism of MMP9 gene." (PMID 20037727, 2009). "Circulating MMP-9 levels are also increased in type 2 diabetes patients with coronary artery disease, and elevated serum MMP-9 concentrations, associated with decreased inhibitor levels (TIMP-1), have been linked to premature coronary atherosclerosis." (PMID 19690647, 2007). "Plasma level of MMP-9 was also an independent risk factor for first time coronary heart disease." (PMID 28771541, 2017). "More detailed studies have recently been performed in middle-aged population by Swedish researchers who found an association of circulating MMP9 levels not only with cardiovascular but also with psychosocial risk factors for coronary artery disease (e.g., depression)." (PMID 20037727, 2009). "Thus, the circulating level of MMP9 was upregulated in coronary artery disease, which may act as a risk factor for evaluating the development and severity of disease." (PMID 31354855, 2019). "This study probes the relationship between serum matrix metalloproteinase-9 (MMP-9) levels, the genetic variant rs17576 in the MMP-9 gene, and the extent of coronary atherosclerosis among Ukrainian patients diagnosed with coronary artery disease (CAD)." (PMID 40224343, 2025). "In coronary artery disease, evening cortisol levels have been shown to have strong positive correlations with the levels of total and active MMP-9, which are significantly elevated in the corneal epithelium and tears of KC." (PMID 41140675, 2025). "Previous studies have shown a significant positive correlation between MMP9 expression and M0 macrophages infiltration in inflammation-related diseases, such as coronary artery disease (CAD), AS, adhesive capsulitis, and cancers." (PMID 38321132, 2024). "Matrix metallopeptidase 9 (MMP9), a collagenase which digests type IV and V collagen of the extracellular matrix which has been identified as a biomarker for coronary artery disease, was found to be down-regulated in both the LV of donors and ICM vs RV83." (PMID 39702518, 2024). "Combined therapy with ezetimibe and rosuvastatin in coronary artery disease patients has similarly resulted in significant reductions in plasma MMP-9 levels, potentially mitigating plaque instability and cardiovascular inflammation." (PMID 39200884, 2024). "The transcriptional activity of the metalloproteinase 9 (MMP-9) gene in the group of healthy men was significantly higher compared to women with coronary artery disease excluded in coronary angiography." (PMID 38540214, 2024). "The analysis also showed the statistically significant higher transcriptional activity of the metalloproteinase 9 (MMP-9) gene in the group of patients with coronary artery disease and heart failure who smoked." (PMID 38540214, 2024). "The analysis also showed the statistically significant higher transcriptional activity of the metalloproteinase 9 (MMP-9) gene in a group of patients with coronary artery disease and heart failure who smoked." (PMID 38540214, 2024). "Considering that there were many studies on MMP9 in ischemic heart disease, the relationship between MMP9 and AMI has been studied." (PMID 37214088, 2023). "It is generally believed that NGAL, NGAL/MMP-9 complex, and cardiovascular disease, especially coronary heart disease and heart failure, are closely related." (PMID 37521280, 2023).
coronary artery disease (continued). "For that reason, serum MMP-9 levels in patients with coronary artery disease are high and correlated with the incidence of cardiovascular events." (PMID 35887981, 2022). "Plasma NGAL showed a better ability in discriminating severe coronary disease than MMP-9, hs-CRP, and IL-1β." (PMID 35410418, 2022). "Increased expression levels of MMP-2 and MMP-9 were confirmed in the expansively remodeled plaques of patients who died from coronary artery disease." (PMID 36142454, 2022). "Studies have shown that MMP-9 activity is related to the severity of coronary heart disease and chronic heart failure." (PMID 35222898, 2022). "Previous studies have revealed that ERK1/2-mediated MMP-9 signaling was involved in ischemic heart diseases." (PMID 34803680, 2021). "Increased circulating levels of MMP-9 have been reported in type 2 diabetes patients with coronary artery disease." (PMID 34829801, 2021). "In patients with angiographically confirmed coronary heart disease (CHD), it was showed that increased concentrations of MMP-9 at baseline were associated with future cardiovascular (CV) death." (PMID 32486345, 2020). "A higher quantity of circulating MMP-9 in patients with coronary artery disease (CAD) seems to predict cardiovascular mortality." (PMID 30513758, 2018). "Further, the MMP-9 concentration in plasma coronary artery disease patients predicts cardiovascular mortality." (PMID 28166283, 2017). "EMMPRIN and MMP-9 represent novel targets to mitigate plaque development and diminish the burden coronary heart disease." (PMID 28261097, 2017). "The reason for the opposing direction of change is unexplained, but precedent exists for differential patterns of MMP-2 and MMP-9 gene expression in coronary heart disease, chronic obstructive pulmonary disease, and thoracic aortic aneurysm." (PMID 27352030, 2016). "Elevation of plasma MMP-2, MMP-9 or both have been observed in coronary heart disease, polypoidal choroidal vasculopathy and Japanese encephalitis." (PMID 27352030, 2016). "While several studies have shown elevated levels in patients with coronary heart disease, results in prospective population based studies evaluating MMP-9 in relation to first time coronary events have been inconclusive." (PMID 26389803, 2015). "For example, increased circulating levels of MMP-9 have been reported in patients with acute coronary syndromes, stable coronary artery disease, and carotid artery stenosis." (PMID 23365489, 2013). "This study was aimed to investigate the prognostic significance of the IL-18+183 A/G polymorphism (rs5744292), single and in coexistence with the matrix metalloproteinase (MMP)-9 -1562 C/T (rs3918242) polymorphism, in patients with stable coronary artery disease (CAD)." (PMID 24040261, 2013). "MMP-9 serum concentration levels have been described in the context of several diseases such as multiple sclerosis, coronary artery disease, multiple myeloma, and chronic lymphocytic leukemia." (PMID 22547904, 2012). "A higher MMP-9 level was also shown to correlate with coronary artery ectasia, and to predict increased mortality in patients with coronary artery disease." (PMID 22672501, 2012). "This agrees with some reports but contrasts to others, which found incremental MMP-9 serum levels in patients with coronary artery disease." (PMID 19751510, 2009). "Higher MMP9 level was also a correlate of coronary artery ectasia and a predictor of increased mortality in patients with coronary artery disease." (PMID 20037727, 2009). "Elevated levels of circulating matrix metalloproteinase-9 (MMP-9) have been demonstrated in patients with established coronary artery disease (CAD)." (PMID 18335048, 2008). "The conducted analyses also revealed a statistically significant difference in the transcriptional activity of the MMP-9 gene in the group of women with coronary artery disease excluded in coronary angiography (A) compared to men from the same group (p = 0.009)." (PMID 38540214, 2024).
coronary artery disease (continued). "Elevated plasma levels of MMP-2 and MMP-9 in coronary heart disease patients correlate with plaque instability and the severity of acute coronary syndrome, making them valuable for predicting these events and diagnosing chronic total occlusion of the coronary artery." (PMID 39200884, 2024). "So, neutrophils are a prominent and early source of MMP-9 in ischemic heart disease." (PMID 35410418, 2022). "We suggest that more serious diseases related to endothelial dysfunction such as coronary artery disease could be prevented by measuring MMP-9 levels." (PMID 34625635, 2021). "Moreover, MMP-9 is a strong independent predictor of atherosclerotic plaque instability in stable coronary heart disease and elevated MMP-9 levels are correlated with the size of the necrotic core of coronary atherosclerotic plaques." (PMID 33814983, 2021). "Significantly elevated MMP-9 levels were measured in the sera of patients with coronary artery disease, and it may contribute to the pathogenesis of that illness." (PMID 33076449, 2020). "Regarding MMP-9, it was demonstrated that its level could be used as a predictor for cardiovascular mortality in patients with coronary artery disease." (PMID 30642049, 2019). "Genetic variation of matrix metalloproteinase 9 (MMP-9) gene polymorphism has been suggested to modulate coronary heart diseases (CHD), yet the underlying mechanisms are not well understood." (PMID 28390432, 2017). "Identifying the effects of the causative factors for the secretion of MMP-9 and TIMP-1 by VSMC may facilitate the understanding of the pathogenesis of coronary heart disease." (PMID 25405958, 2015). "Patients with coronary artery disease were recently shown to have increased levels of MMP-9." (PMID 22672501, 2012). "The higher level of MMP9 in patients with coronary artery disease has been recently reported." (PMID 20037727, 2009). "Serum MMP-9 may reflect a systemic inflammatory state, but genetic variation may also contribute to the MMP-9 levels and activity and thereby to the risk of coronary artery disease." (PMID 29349668, 2018). "We therefore hypothesised MMP-1 and MMP-9 serum levels to be associated with non-calcified lesions as determined by CT-angiography in patients with coronary artery disease." (PMID 19751510, 2009). "So far, most studies exploring elevated levels of MMP-9 and its association to coronary artery disease (CAD) have been based on a experimental or clinical design, the latter showing elevated levels of plasma MMP-9 in patients with CAD." (PMID 18335048, 2008). "Common variables considered were demographic factors like age and sex, clinical parameters such as CVRFs, dyslipidemia, and coronary artery disease, and markers like oxidized LDL and MMP-9." (PMID 40217703, 2025). "In a randomized clinical trial involving coronary artery disease patients, the MMP-9 inhibitor curcumin was effective in preventing vascular diseases and suppressing MMP-9 expression." (PMID 40565017, 2025). "Elevations of MMP-9 and MPO are in line with previous studies showing high levels of MMP-9 and MPO in obese individuals, and with that they are among the most up-regulated genes in coronary heart disease." (PMID 37430349, 2023). "The plasma levels of MMP-1, MMP-7, MMP-8, MMP-9, and MMP-10 are elevated in patients with coronary artery disease (CAD), whereas those of MMP-2 and MMP-3 levels are decreased." (PMID 36142454, 2022). "Thus, MMP9 may be related to the etiology of coronary artery disease in KD." (PMID 33868359, 2021). "E.g., neutrophils from patients with coronary artery disease (CAD) are more prone to release these mediators, particularly MMP-9, upon in vitro stimulation compared with neutrophils from healthy subjects." (PMID 30726210, 2019).